TNF (tumor necrosis factor)
Diseases named in the same sentence as TNF in open-access papers (continued):
Sharing a sentence is not in itself a finding about the gene and the disease.
tumor (continued). "NPs acted as immunomodulatory and radiosensitizing agents and induced tumor cell death, which was related to increased ROS levels, the production of TNF-α, and chemotaxis of macrophages." (PMID 35954362, 2022). "Previous studies have reported that ROS activation and tumor TNF-α production are accompanied by an elevation of free fatty acids and cholesterol accumulation in mitochondria, which leads to liver damage and HCC development." (PMID 35840761, 2022). "In a mouse model of PDA, Clec7a deletion significantly reduced the infiltration of PDA with F4/80+, CD206+ and Arg1+ TAMs, as well as upregulated MHCII, TNF-α and iNOS expression in tumor." (PMID 36686729, 2022). "Oncolytic viruses with TNF-α can eradicate tumors and induce antitumor T-cell responses in various tumor models." (PMID 36145559, 2022). "Classical nude mouse xenotransplantation studies have shown that BCG inhibits tumor clearance induced by TNF-α and promotes tumor formation." (PMID 35525982, 2022). "Although many studies have shown the multifarious effects of TNFα in tumor progression in various cancers, several questions remain unaddressed with regard to the complex biological signaling of this pleotropic cytokine in the tumor microenvironment." (PMID 36290384, 2022). "In a murine cancer model granulocytic myeloid-derived suppressor cells (G-MDSCs also known as PMN-MDSCs) and TANs induced CD8 T-cell apoptosis via the TNF-α pathway and NO production, thereby promoting a tumor-supportive environment." (PMID 35784290, 2022). "Ruminococcus and Alistipes species were found to be significantly depleted by antibiotics, and administration of Alistipes shahii species to antibiotic-treated mice was able to restore TNF production in tumor-infiltrating myeloid cells." (PMID 35474500, 2022). "There were also trends of increasing CCL3 and TNF-α expression in the tumor cells, indicating a slight pro-inflammatory effect in the solid tumors." (PMID 35513776, 2022). "M2 macrophages, which occupy the majority of TAM, can produce a variety of pro-angiogenic factors such as VEGF-A and tumor necrosis factor α (TNFα) in hypoxic areas to maintain tumor growth." (PMID 36372883, 2022). "While a set of values of pulse period, pulse duration, and TNF concentration was optimal to reduce the number of alive tumor cells, different sets of values turned the cells resistant to TNF." (PMID 35463947, 2022). "Under IFN-γ priming, MSCs increase the expression of class II histocompatibility leukocyte antigen (HLA) molecules, and MCSs preconditioning with IFN-γ and TNF-α in combination promoted angiogenesis and accelerated tumor growth." (PMID 35326438, 2022). "It is reported that MET, induced by tumor inflammatory stimuli such as TNF-α, is essential for neutrophil chemoattraction and cytotoxicity in response to its ligand hepatocyte growth factor (HGF)." (PMID 35784290, 2022). "Further in-depth study of each signaling pathway verified that monocytes were directly associated with tumor cells only in the MIF and TNF pathways, in which the most important ligand-receptors were CD74/CD44 and TNF/TNFRSF1B." (PMID 36479092, 2022). "H2O2 also induces secretion of chemokines and cytokines by IECs through the tumor necrosis factor α (TNFα) autocrine loop to recruit myeloid cells and promote tumor invasion." (PMID 36158661, 2022). "Daintain/AIF-1 promotes tumor cell migration by upregulating TNF-α via activating the p38 MAPK signaling pathway in BRCA." (PMID 35251139, 2022). "We next evaluated the tumor-inflammation relationship using TNFα, a pro-inflammatory cytokine, as a probe." (PMID 35804814, 2022). "It is now known that polyphenolic compounds can affect the functioning of receptors for cytokines such as tumor necrosis factor alpha (TNF-α) or some interleukin receptors, which can be used in tumor therapy." (PMID 36172282, 2022).
tumor (continued). "In a DEN induced tumor model, deletion, or inhibition of TNFα resulted in reduced tumor incidence accompanied by suppressed activation and proliferation of hepatic progenitors via the TNFR2-STAT3 pathway." (PMID 36276076, 2022). "This research led to the discovery of a strong induction of the angiogenic cytokine vascular permeability factor/vascular endothelial growth factor by TNF, and consequently, a pro-tumor function of TNF in tumor angiogenesis and vascular permeability." (PMID 36358688, 2022). "The correlation research indicated hypoxic stress can initiate tumor necrosis because of accelerated tumor development and insufficient blood flow and TNF-α has long been recognized to engender cancer necrosis." (PMID 36119049, 2022). "M1-TAMs play a key role in killing tumor cells by producing reactive oxygen/nitrogen species (ROS/RNS) and pro-inflammatory cytokines such as IL-1β, IL-6, and TNF-α, and thus M1-TAMs are macrophages with anti-tumor effects." (PMID 35479325, 2022). "Inflammation contributes to tumor development, and overproduction of the pro-inflammatory factor TNF can both induce tumor cell progression." (PMID 36003525, 2022). "Pro-inflammatory cytokines IL-6, IL-1β and TNF-α were found to be higher in tumor-control group compared to normal control animals." (PMID 35197512, 2022). "A butanol extract prepared from the cell-free supernatant of B.adolescentis significantly increased the production of TNF-α and NO, which regulated immune modulation and repressed tumor growth." (PMID 36144335, 2022). "At the same time, oral administration of glucomannan as a dietary supplement at the 4 mg dose increased TNF-α and IL-17 cytokine responses in tumor-bearing mice compared to the control groups." (PMID 36298611, 2022). "Immune genes previously linked to a suppressive tumor microenvironment in WTs (TGFB1, IL10) are highly expressed in all EX2 tumors whilst activating genes (TNF, IL6) show a more restricted expression pattern." (PMID 36230794, 2022). "NK cells also produce TNF-α and NK cells exert anti-tumour functions by inducing apoptosis through TNF-α." (PMID 36698840, 2022). "Tumor-infiltrating MPCi-conditioned T cells showed an increase in cells double positive for the effector cytokines IFNγ and TNF." (PMID 35452600, 2022). "NF-κB is important for the formation of inflammatory sites inside the tumor by inducing gene expression of inflammatory cytokines, most notably TNF-α, IL-1, and IL-6." (PMID 36429054, 2022). "Tumor cell with elevated canonical JNK signaling via Eiger/TNF, dTAK1/JNKKK, and Hep/JNKK grows in a Bsk/JNK-dependent manner." (PMID 36222503, 2022). "Another study demonstrated that the combination of CAR-T cells and modified OVs expressing TNF-α and IL-2 has a robust anti-tumor effect in the pancreatic ductal adenocarcinoma (PDA) murine model." (PMID 36419058, 2022). "HMGB1 is actively secreted by innate immune cells, including monocytes, macrophages, and polymorphonuclear neutrophils in response to either LPS or TNF-α stimulation, and is released from damaged and tumor cells." (PMID 36078108, 2022). "Our findings further demonstrate that TNFα stimulation in BCSCs has the ability to instigate distinct cellular communication within the tumor microenvironment, inducing intra-tumoral stromal invasion." (PMID 36290384, 2022). "The change in the tumor tissue level of TNF-α in different groups was assessed to gain an insight into the inflammatory milieu (and Supplementary 6)." (PMID 35798765, 2022). "Lastly, a low dose of TP and TNF-α inhibited the tumor weight and tumor volume of AGS and MKN45 cells in vivo." (PMID 36110523, 2022). "In the tumorigenesis process, tumor cells promote tumor spread and metastasis through inflammation by releasing TNF-α, IL-6, IL-1, and interferon factors, which in turn stimulate tumor cell growth, motility, and invasion." (PMID 36233009, 2022).
tumor (continued). "The tumor-derived tumor necrosis factor (TNF) or other inflammatory factors can induce MET in human neutrophils, leading to transmigration neutrophils across an activated endothelium, and free radical production results in cancer cell killing." (PMID 35986321, 2022). "Both an increased number of CD11b+ myeloid cells (left) and an increase in the percent of CD11b+ cells producing TNF-α (right) significantly correlated with decreased tumor burden." (PMID 35140221, 2022). "The most protruding TME member in these cells is the tumor-associated macrophages (TAMs), which mediate tumor proliferation by secreting growth factors and inflammatory mediators such as CCL2, IL-1α, IL-6 and TNF-α and induce treatment resistance in cancer." (PMID 35736173, 2022). "It was reported that adipocyte cells secreted leptin, TNF, IL-6, and adiponectin to induce a change in tumor gene expression related to angiogenesis signatures." (PMID 36014894, 2022). "For example, studies have demonstrated that TNF‐α acts like a vascular disrupting agent in the initial stage of tumor colonization by Salmonella typhimurium, allowing the bacteria to be flushed into the tumor along with the blood." (PMID 35522104, 2022). "By targeting TLR8, these two exosomal miRNAs dominate the initiation of NF-κB pathway to mediate TNF-α and IL-6 emitting, thus inhibiting tumor propagation and expansion." (PMID 35663957, 2022). "There is experimental evidence showing that TAMs play an additional role with their direct effect on tumor cells and also through immune system modulation with cytokine secretion (e.g., TNF- α, IL-6, and IL-1β)." (PMID 36077144, 2022). "mediated pathways, activating NF-κB and TNF signaling pathways, linking the tumor microenvironment with tumor cells, and playing an important regulatory role in the overall tumorigenesis and development." (PMID 35814477, 2022). "Many of these proangiogenic factors are induced by inflammatory mediators, such as tumor necrosis factor (TNF)-α, acting on tumor and stromal cells via the nuclear factor kappa B (NF-κB) pathway." (PMID 35267534, 2022). "We found that TNF expression was upregulated in CC tissues and its high expression predicted low survival, suggesting that it acts as a tumor-promoting gene in our study." (PMID 35574296, 2022). "Ki67 expression, the number of CD8 + T cells, and the ability to produce IFN-γ and TNF-α in tumor tissues were determined." (PMID 35485300, 2022). "Initially, in the control and in the early stages of the tumor, the IL-1β levels show a significant scatter among individuals, whereas those of TNFα and IL-10 have a narrower spread." (PMID 35053477, 2022). "TNF-α can exhibit varying effects on the tumor microenvironment (TME) and hence be responsible for tumor progression and suppression." (PMID 36059323, 2022). "For instance, TNF-α is a master regulator of the inflammatory response, overexpressed and secreted in the neoplasm microenvironment." (PMID 36091778, 2022). "CD40/CD40L signaling strengthens Nitric oxide synthase 2 (NOS2) expression, and production of nitric oxide and TNF-α through CD40 contributes to tumor elimination by adoptive cell transfer." (PMID 35806328, 2022). "At day 19, the tumor in the ADP group grew to 4 cm3, while the tumor in the ADP@SWNT/TNFα group was only 1.8 cm3." (PMID 34994069, 2022). "Nuclear factors binding to the AP-1 and NF-κB promoters are induced and synergistically contributed by TPA and TNF-α in tumor cell invasiveness." (PMID 35840633, 2022). "Tumor necrosis factor -α (TNF-α) plays an important role in shaping the tumor microenvironment and coordinating tumor-microenvironment interaction." (PMID 36118769, 2022). "HIF-1α expression is positively regulated by TNF-α, a major inflammatory cytokine that induces necrosis in certain tumor types." (PMID 35372052, 2022). "They release tumor killing molecules such as TNF-α, reactive oxygen radicals and nitric oxide, or actively take up cancer cells by phagocytosis." (PMID 35163566, 2022).
tumor (continued). "For example, signals from TNF-alpha, IL-17, and IL-6 appear to foster a tumor-supportive microenvironment, probably via mitogenic changes, which can impact epithelial cell migration and survival programs." (PMID 35563010, 2022). "Hypoalbuminemia usually reflects insufficient oral intake and excessive tumor consumption that induces inflammatory cytokines such as IL-1, IL-6, and TNF-α." (PMID 36194563, 2022). "Tumor necrotic factor-alpha (TNF-α) is an inflammatory cytokine that results in apoptosis and necrosis and is also a mediator of tumor regression, an effector of cachexia amongst other functions." (PMID 35291755, 2022). "Tumor necrosis factor alpha (TNF-α) pathway: a conserved signaling pathway regulated by TNF-α that is involved in inflammatory responses and tumor necrosis." (PMID 35319749, 2022). "After the NLRP3 inflammasome is activated, it causes an inflammatory cascade reaction, leading to the release of pro-inflammatory factors such as IL-1β, IL-18, IL-22, TNF-α, and the activation of inflammation-tumor signaling pathways such as NF-κB." (PMID 35292015, 2022). "Mice receiving WJR treatment had higher levels of IFN-γ and TNF-α in tumor tissues and in serum, suggesting enhanced host cellular immunity." (PMID 36212428, 2022). "Interleukin (IL)-6 and other proinflammatory cytokines, including tumor necrosis factor, are released by inflammatory cells in the tumor microenvironment in response to tissue necrosis and the presence of tumor cells." (PMID 36096761, 2022). "Although, TNF-a is basically a pro-tumorigenic cytokine, it shows, like many other immunologic effectors in the tumor microenvironment, a dual functionality, which makes it difficult to puzzle out its true effects on cancer immunosurveillance." (PMID 36077865, 2022). "Overall, our results indicated the valid inhibitory effect of NIR‐triggered ADP@SWNT/TNFα on tumor cells." (PMID 34994069, 2022). "CAR-T20 increased human IFN-γ, murine TNF and murine IL-6 levels and decreased human IL-10 levels in tumor-bearing mice." (PMID 36352168, 2022). "Drosophila RasV12scrib−/− eye imaginal disc tumor cells secret IL-6 through tumor necrosis factor (TNF)‒JNK‒Fos pathway in response to TNF stimulation." (PMID 34459894, 2022). "M1 polarized macrophages are activated by TNFα and IFNγ and promote pro-inflammatory activity, which supports the cytotoxic potential and possesses anti-tumor functions." (PMID 35736195, 2022). "Based on the ability to sensitize cells for TNF-induced cell death, the TWEAK/Fn14 system has obviously the potential to suppress together with TNF tumor development." (PMID 36339601, 2022). "The AAVP-mediated systemic delivery of TNF-α led to the tumor-specific expression of this cytokine, which provides apoptosis in the vasculature and tumor necrosis." (PMID 36430720, 2022). "TNF-α is also involved in tumor cell proliferation by increasing fibrinogen activator inhibitor type 2 (PAI-2), which is assumed to protect cells from apoptosis." (PMID 35574296, 2022). "In response to proinflammatory responses, such as LPS, TNF-α, or IL-1β, tumor cells produce CCL2 dependent on the activation of the constitutive nuclear factor -κB (NF-κB) pathway." (PMID 35281057, 2022). "Cytokines are types of proteins that mediate the interaction between cells in the TME, including TNF, interleukins, chemokines, and growth factors, and regulate tumor progression and stromal cells." (PMID 35707536, 2022). "On the contrary, IL-32γ isoform is shown to diminish the levels of cytokines that promote tumor growth such as TNF-α, IL-1β, and IL-6, whereas the levels of IL-10 cytokine, a tumor growth-inhibiting cytokine, were elevated." (PMID 35281008, 2022). "Overall, our findings indicate that sTNFR1 and sTNFR2 inhibit the ability of TNFα-stimulated TNBC cells to release pro-metastatic chemokines that play key roles in tumor progression." (PMID 35884574, 2022).
tumor (continued). "IL-2-activated NK cells in presence of l-kynurenine show impaired expression of the activating receptors NKp46 and NKG2D, lower production of IFN-γ and TNF-α, and reduced cytotoxicity against tumor cells." (PMID 36713558, 2022). "In the tumor microenvironment, TNF-α was upregulated and IL-6 was down-regulated significantly in nanovaccine group." (PMID 35418151, 2022). "When TNF-α was originally recognized to have a role in hemorrhagic necrosis, transplanted tumours were shown to be more vulnerable." (PMID 35813433, 2022). "Proinflammatory cytokines produced by the tumor, such as IL-1a, IL-1b, IL-6, and TNF-α, can cross the blood–brain barrier (BBB) and migrate to the brain." (PMID 35736871, 2022). "The consequent overproduction of key cytokines (IL-1β, IL-6, and TNF-α) played an important role in the exacerbated tumor burden in the AOM/DSS + Abx + Akk group." (PMID 36312913, 2022). "FimH combined with OVA can promote antigen-specific immune activation, promote T cell proliferation and IFN-γ and TNF-α production, increase the tumor infiltration of Teff cells and inhibit the growth of melanoma in mice." (PMID 35956752, 2022). "Although many mechanisms make TNF-α a formidable favoring factor of tumor genesis, several mechanisms are included in the category of neoplasia counteracting." (PMID 35563587, 2022). "TNFα is a cytokine that achieves tumour killing both through direct induction of apoptosis and recruitment of other immune cells to activate cell‐mediated cytotoxicity and disrupt tumour neoangiogenesis." (PMID 35758207, 2022). "For instance, inosine enhanced cytokine production (granzyme B, IFN-γ and TNF-α) and the tumor killing capacity of T cells, even in glucose-deprived conditions." (PMID 36358860, 2022). "The sensitivity of tumor cell lines to TNF-α is very different, and TNF-α can even stimulate a few tumor cells." (PMID 36035842, 2022). "TNF, the only up-regulated hub protein, functions as a tumor stimulator or suppressor, depending on the organ, cell, and carcinogen." (PMID 35563525, 2022). "Activation of MERTKR in TAM promotes tumor progression by inducing the expression of the proinflammatory cytokines, IL-1β, IL-6, and TNF." (PMID 36679900, 2022). "When the function of hILC1s was impaired, TNF-α production decreased, resulting in a pro-tumor effect in patients with tumor." (PMID 36246629, 2022). "We found that tumor-targeted human MCs from adipose and peripheral blood bound to cancer cells and induced apoptosis in vitro through the FcεRI-mediated release of TNF-α." (PMID 35740607, 2022). "Secretion of growth factors such as VEGF, EGF, FGF, HGF, PDGF, TGF-β, and TNF-α from the primary tumor promotes angiogenesis." (PMID 36359888, 2022). "The anti-tumor activity of TNFα is now well established, and approximately 28% of cancers are susceptible to direct cell killing by soluble TNFα." (PMID 35593465, 2022). "Metabolic imbalances in the skeletal muscle are mediated by tumour-derived pro-inflammatory cytokines, such as tumour necrosis factor-α (TNF-α), interleukin-1 (IL-1), IL-6, and transforming growth factor β1 (TGFβ1)." (PMID 35406121, 2022). "DCs also promote anti-tumor immunity by secreting proinflammatory cytokines, including IL-6, TNFα, and type I and II interferons (IFNs)." (PMID 36248881, 2022). "TAM-derived TNF-α upregulates the expression of programmed death 1 ligand 1 (PDL-1) on tumor cells, thereby inhibiting the function of T cells, natural killer (NK) cells, and activated dendritic cells (DCs)." (PMID 35326602, 2022). "These cytokines are expressed in an altered manner; IL-1β, TNF-α, IL6, IL10, IFN-γ, and CX3CL1 are overexpressed and are correlated with the onset of pain, as it was discovered that they are linked to tumor progression and aggressiveness." (PMID 35054779, 2022).